CXCL12 (C-X-C motif chemokine ligand 12)
Diseases named in the same sentence as CXCL12 in open-access papers (continued):
Sharing a sentence is not in itself a finding about the gene and the disease.
hepatocellular carcinoma (continued). "In the pre-metastatic microenvironment of hepatocellular carcinoma, the expression of CXCL12 can downregulate the transcription factor Paired Related Homeobox 1 (Prrx1), thereby inducing an increase in the protein and mRNA expression of CXCR4 in hepatocellular carcinoma cells via the STAT3 pathway." (PMID 38920657, 2024). "For instance, CXCL12 is activated by SOX4 to drive the process of hepatocellular carcinoma." (PMID 35294319, 2022). "Furthermore, secretion of CXCL12/SDF1 by hepatic carcinoma-derived CAFs attracts monocytes into the tumor stroma and engages their differentiation into MDSCs in an IL-6- and STAT3-dependent manner." (PMID 36338519, 2022). "SDC4 is essential for SDF-1 (CXCL12) induced migration and invasion of hepatoma cells." (PMID 34282767, 2021). "Moreover, SDC4 is essential for CXCL12-induced migration and invasion of hepatoma cells and human cervix carcinoma (HeLa) cells." (PMID 34282767, 2021). "Furthermore, more studies are needed to explore the specific function of the CXCL12/CXCR4/CXCR7 axis in hepatocellular cancer." (PMID 30574021, 2018). "Furthermore, we showed that autologous chemotaxis influences this interstitial fluid flow-induced invasion of hepatocellular carcinoma derived cell lines via the C-X-C chemokine receptor type 4 (CXCR4)/C-X-C motif chemokine 12 (CXCL12) signaling axis." (PMID 26560447, 2015). "Moreover, CXCL12 and CXCR4 polymorphisms appear to contribute to increased risk of hepatocellular carcinoma (HCC) and may be potential markers for HCC." (PMID 33363463, 2020). "Moreover, CXCL12 produced by cancer associated fibroblasts can recruit MDSCs to the tumor microenvironment to exert tumor-promoting effects in mouse model of hepatic carcinoma and estrogen receptor-negative breast cancer." (PMID 30813533, 2019). "Similarly, CAFs from hepatic carcinomas attract monocytes to the TME by their secretion of CXCL12/SDF1 and induce their differentiation into MDSCs through IL-6-mediated STAT3 activation, thus altering T cell proliferation and functions, as well as the patients overall survival." (PMID 29545811, 2018). "Similarly, in hepatocellular carcinoma, characterized by persistent Notch activation, hypoxia may induce CXCL12 upregulation, that in turn promotes the recruitment of Tregs and M2-type macrophages." (PMID 30154786, 2018). "The chemokine CXCL12 significantly stimulated migration of Huh-7 (Fluorescence: 30880±3298 IE vs 15705±1801 IE; P=0.001), but not of Hep3B (Fluorescence: 14367±2694 IE vs 15885±1559 IE; NS) or HepG2 (Fluorescence: 7608±110 IE vs 7956±416 IE; NS) hepatoma cells." (PMID 16819541, 2006). "The TAM-derived PAI-1 then enhances hepatocellular carcinoma (HCC) malignancy through epithelial–mesenchymal transition (EMT), highlighting the CAF/TAM/PAI-1/CXCL12 axis as a potential therapeutic target." (PMID 41601623, 2026). "In hepatocellular carcinoma CAF promotes hepatocellular carcinoma progression by promoting macrophage M2 polarization and inducing PAI-1 secretion via CXCL12." (PMID 40357367, 2025). "Chemokines and their receptors, acting as axes such as CXCL12/CXCR4, play a crucial role in shaping the tumor microenvironment (TME) and influence the progression of hepatocellular carcinoma (HCC)." (PMID 40145607, 2025). "FOXC1 and FOXC2 were required for intestinal regeneration by stimulating paracrine CXCL12 and Wnt signaling, and FOXP1 downregulation inhibited G1/S phase cell cycle arrest by inducing the proliferation of hepatocellular carcinoma." (PMID 38192721, 2023). "Downregulation of CXCL12/CXCR4 signalling enhanced sensitivity to chemotherapy and impaired tumour growth in a xenograft mouse model of hepatocellular carcinoma." (PMID 36284271, 2022). "For example, TCF12 expedites hepatocellular carcinoma (HCC) by upregulating CXCR4 and its ligand CXCL12 and activating the MAPK/ERK and PI3K/AKT pathways." (PMID 33413401, 2021).
hepatocellular carcinoma (continued). "The expression of SDF-1—also called CXC motif chemokine ligand 12 (CXCL12), intercrine reduced in hepatomas (IRH), and pre-B cell growth-stimulating factor—is expressed in many cell types (i.e., fibroblasts, myoblasts, muscle fibers)." (PMID 33019579, 2020). "High levels of CXCL12 and CXCR4 were reported in sinusoidal endothelial cells in Hepatocellular Carcinoma (HCC) specimens." (PMID 32260318, 2020). "On this regard, recently we reported that CXCL12/CXCR4 axis is involved in migration and invasion of osteosarcoma and hepatocellular carcinoma cell lines through EMT activation." (PMID 29069870, 2017). "Likewise, increased levels of CXCL10, CXCL12, and CXCL14 in hepatocellular carcinoma patients correlated with favorable survival rates." (PMID 38275602, 2024). "Finally, the GPCR ligand stromal cell-derived factor 1 (SDF-1), also known as CXC motif chemokine ligand 12 (CXCL12), induced mitochondrial superoxide dismutase 2 expression in human hepatocellular carcinoma cells." (PMID 39000269, 2024). "Whereas conditioned media from hepatoma cells did not facilitate the CXCL12 expression in LX2 cells, LX2 significantly stimulated CXCL12 production of hepatomas, especially of HuH7, both in direct contact and via conditioned medium." (PMID 37762298, 2023). "By comparing the mRNAs in the ceRNA subnetwork with the mRNAs in the PPI subnetwork, three common mRNAs (ESR1, CXCL12 and IRF4) were obtained, which should play an important role in the development of hepatocellular carcinoma and used as follow-up research objects." (PMID 36855431, 2023). "It was discovered that CAFs from hepatocellular carcinoma impact T cell development and function, as well as the patient’s overall longevity, by enticing monocytes to the TME by releasing CXCL12 and driving them to transform into MDSCs by activating STAT3 through IL-6." (PMID 37007004, 2023). "Notably, overexpression of SOX4-mediated CXCL12 promoter in HCC cells enhanced tumor-induced angiogenesis, contributing to distant tumor metastasis and poor prognosis in hepatocellular carcinoma (HCC) patients." (PMID 35573654, 2022). "Matrix metalloproteinase 10 promotes angiogenesis, growth, and diffusion of human hepatocellular carcinomas by regulating the CXCL12/CXCR4 axis, and the phosphatase and tensin homolog can negatively regulate the expression of CXCL12/CXCR4 in prostate tumors, thereby controlling tumor growth." (PMID 33710803, 2021). "Chemokine ligand 12 (CXCL12; stromal cell-derived factor 1) is a homeostatic chemokine that signals through chemokine receptor 4 (CXCR4), which plays an important role in the proliferation of hepatoma cells." (PMID 23737842, 2013). "In hepatoma cells, exposure to CXCL12 increased proliferation and invasion of Huh7, but not of Hep3B or HepG2 cells." (PMID 16819541, 2006). "In the human hepatocellular carcinoma, APS can relieve the immune-suppressive effects of Treg cells by restoring the balance of cytokines in the TME, suppressing the expression of FOXp3 mRNA or inhibiting Treg cell migration by blocking SDF-1 and its receptor via the CXCR4/CXCL12 pathway." (PMID 37741920, 2023). "In the case of hepatocellular carcinoma the intracellular expression of CXCR4 with lack of its expression at the cell surface and lack of response to its ligand CXCL12 has been reported." (PMID 24559071, 2014).
gastric cancer (85 papers, 2010 to 2025). A primary or metastatic malignant neoplasm involving the stomach. "This consistent expression pattern among these invasion-associated proteins in gastric cancer highlights the significance of the DARPP-32/CXCR4/CXCL-12 axis in promoting invasion." (PMID 39767693, 2024). "We then evaluated the association of CXCL12 expression and the anti-PD-1 response in gastric cancer patients." (PMID 34911533, 2021). "It has been reported that CXCL12 plays an important role in cancer progression and immune evasion, and we questioned whether CXCL12 is implicated in gastric cancer progression and anti-PD-1 therapy resistance." (PMID 34911533, 2021). "Furthermore, circDLG1 expression was significantly associated with CXCL12 in gastric cancer tissues." (PMID 34911533, 2021). "Accordingly, the suppressed cell migration ability caused by CXCL12 knockdown could be restored by circDLG1 ectopic expression in gastric cancer cells." (PMID 34911533, 2021). "In addition, miR-141-3p expression was inversely associated with CXCL12 expression in gastric cancer tissues." (PMID 34911533, 2021). "The CXCL12/CXCR4 axis is highly relevant to human gastric cancer, where it promotes invasion, metastasis, and therapeutic resistance." (PMID 40673273, 2025). "Overexpression of circDLG1 in gastric cancer (GC) enhances CXCL12 expression by sponging miR‐141‐3p to promote stemness, anti‐PD‐1 therapy resistance, and MDSCs infiltration." (PMID 40356340, 2025). "For example, elevated serum CXCL12 levels have been reported in patients with advanced gastric carcinoma and head and neck cancers compared with healthy individuals." (PMID 40849508, 2025). "Elevated expression of CXCR4 and/or CXCL12 expression has been examined in larger tumors and lymphatic invasion samples in gastric cancer, as well as decreased response to radio- and chemo-therapy in various cancer types." (PMID 38748299, 2024). "Chemokines produced by CAFs like CXCL12 also promote tumor progression and invasiveness of gastric cancer cells by clustering integrin β1 proteins on gastric cancer cells." (PMID 38562556, 2024). "With a deeper understanding of these mechanisms, the DARPP-32/CXCR4/CXCL-12 complex axis should be considered a type of targeted therapy to inhibit tumor progression and improve outcomes in patients with gastric cancer." (PMID 39767693, 2024). "Meanwhile, disrupting CXCL12/CXCR4-mediated signaling pathways also contributes to inhibiting further metastasis of gastric cancer at a later stage." (PMID 37047625, 2023). "We also added CXCL12, INHBA, THBS1, and THBS2 to the correlation analysis since they are suggested as CAF markers associated with an aggressive phenotype in gastric cancer." (PMID 35739492, 2022). "In addition, CXCL12 was down-regulated in gastric cancer tissues, accompanied by hypermethylation, and the reduced CXCL12 expression was closely associated with lymph node metastasis and histological grading, presumably playing a possible part in gastric cancer cell metastasis." (PMID 35770088, 2022). "In gastric cancer, high-expressed CXCL12 and CXCR4 have been found to promote the migration, invasion and EMT of gastric cancer cells, and are closely related to the poor prognosis." (PMID 35264069, 2022). "It was previously reported that metastasis was associated with the CXCL12/CXCR4 axis in many tumors, including gastric cancer." (PMID 35877436, 2022). "Our study revealed the significance of the circDLG1/CXCL12 axis in the immune evasion and anti-PD-1 resistance of gastric cancer." (PMID 34911533, 2021). "Mechanistically, circDLG1 interacted with miR-141-3p and acted as a miRNA sponge to increase the expression of CXCL12, which promoted gastric cancer progression and resistance to anti-PD-1-based therapy." (PMID 34911533, 2021).
gastric cancer (continued). "qRT–PCR analysis showed that knockdown of circDLG1 significantly decreased the expression of CXCL12, whereas ectopic expression of circDLG1 significantly increased CXCL12 expression in gastric cancer cell lines." (PMID 34911533, 2021). "The aim of this study was to determine the relationship between CXCL12 expression in CAFs and the malignant progression of gastric cancer (GC)." (PMID 33854601, 2021). "In gastric cancer, C-X-C motif chemokine 12 (CXCL12) derived from CAFs promotes cell invasion by enhancing the clustering of integrin β1 in gastric cancer cells." (PMID 30814977, 2019). "Cancer-associated fibroblasts (CAFs) are apparently responsible for the invasion process and metastatic actions in some cancers, among them gastric cancer is titled, through the activation of CXCL12/CXCR4 signalling." (PMID 29867026, 2018). "Serum CXCL12 levels in patients with esophageal cancer were measured at 1.27 ng/ml compared to 0.86 ng/ml in healthy controls, while gastric cancer tumors were approximately 3618 ng/ml compared to 1715 ng/ml in the non-cancer control group." (PMID 29596520, 2018). "We demonstrate that DC-SIGNR facilitates gastric cancer liver metastasis mediated by HNRNPKP2 regulated by STAT5A via the CXCL12/CXCR4 biological axis." (PMID 28403883, 2017). "It has been demonstrated that cancerous CXCL12 positivity was determined to be an independent prognostic factor for patient survival of gastric cancer." (PMID 23936528, 2013). "It has been reported that metastasis was associated with chemokine signaling through the CXCL12/CXCR4 axis in many tumors, including gastric cancer." (PMID 23936528, 2013). "Suppression of CXCR4 expression by plumbagin was found to correlate with the inhibition of CXCL12-induced migration and invasion of both breast and gastric cancer cells." (PMID 21880153, 2011). "We further investigated the effect of plumbagin on CXCL12-induced migration and invasion of both breast and gastric cancer cells." (PMID 21880153, 2011). "We found that preincubation of cells with plumbagin completely blocked CXCL12-induced migration and invasion of both breast and gastric cancer cells." (PMID 21880153, 2011). "Our subsequent validation studies using a group of independent patients showed that the GPCR-ligand CXCL12 is expressed in tumour cells of the majority of gastric carcinomas." (PMID 20386750, 2010). "The translation and histoanatomical distribution of CXCL12 was subsequently studied by immunohistochemistry in 347 gastric carcinoma samples." (PMID 20386750, 2010). "There is some evidence that CXCR4 expressing gastric carcinomas more likely develop a peritoneal spread of the tumour, and malignant ascites contains high concentrations of CXCL12." (PMID 20386750, 2010). "SDF-1 (CXCL12) is clinically significant as it promotes cancer cell migration, invasion, and metastasis in human gastric cancer through interaction with its receptor CXCR4, and high SDF-1 expression is associated with poor prognosis and increased lymph node metastasis." (PMID 40673273, 2025). "Additionally, DARPP-32 significantly impacts CXCR4 and CXCL-12 expression, critical for invasive behavior in gastric cancer." (PMID 39767693, 2024). "An attempt to understand the function of Tc17 cells in gastric cancers using ex vivo experiments showed that Tc17 cells isolated from the gastric tumor can stimulate tumor cells to produce CXCL12, which consequently recruit myeloid-derived suppressor cells (MDSCs) to suppress cytotoxic CD8+ T cells." (PMID 35999201, 2022). "The results of clone formation and transwell assays showed that the addition of the CXCL12/CXCR4 signaling pathway by the inhibitor, AMD3100, reverses the increase in the proliferation and migration of gastric cancer cells that was caused by KDM6B ectopic expression." (PMID 36564369, 2022).
gastric cancer (continued). "For example, CXCL12 secreted from CAFs promotes gastric cancer invasiveness by increasing the clustering of integrin β1 in gastric cancer cells and may lead to tumor progression via increased focal adhesion kinase (FAK) signaling." (PMID 35300411, 2022). "The results showed that ectopic expression of miR-141-3p could significantly decrease the mRNA level of CXCL12 in gastric cancer cells." (PMID 34911533, 2021). "In this study, we showed that knockdown of CXCL12 could inhibit the invasion ability and improve the sensitivity of gastric cancer to anti-PD-1 therapy." (PMID 34911533, 2021). "Indeed, previous studies have indicated that CXCL12 is involved in the progression and metastasis of gastric cancer." (PMID 34911533, 2021). "In addition, CXCL12 was one of the most significantly decreased genes by knockdown of circDLG1 in gastric cancer cells based on the RNA sequencing assay." (PMID 34911533, 2021). "Taken together, these data demonstrated that CXCL12 might be used as a biomarker to predict gastric cancer resistance to anti-PD-1 therapy." (PMID 34911533, 2021). "Mechanistically, circDLG1 could directly interact with miR-141-3p, acting as a miRNA sponge to increase the expression of the miR-141-3p target gene chemokine 12 (CXCL12), thereby promoting the progression of gastric cancer." (PMID 34911533, 2021). "The potential role of CXCL12 was further explored in gastric cancer cells." (PMID 34911533, 2021). "In addition, univariate and multivariate regression analysis indicated that CXCL12 in CAFs was a variable to predict the prognosis of patients with gastric carcinoma." (PMID 33854601, 2021). "CXCL12 induces migration via Src-mediated CXCR4-EGFR cross-talk in gastric cancer cells." (PMID 32903764, 2020). "CXCL12 is highly expressed by peritoneal mesothelial cells, and higher levels of CXCL12 are detected in malignant ascites fluid from patients with peritoneal metastasis of gastric cancer." (PMID 33230476, 2020). "CXCR4 positivity of primary gastric carcinoma also significantly correlated with the development of PM, suggesting that the CXCR4/CXCL12 axis might play an important role in the development of PM from gastric carcinoma." (PMID 31198853, 2019). "In addition, we previously reported that Cxcl12/Cxcr4 signaling is involved in activation and recruitment of cancer-associated fibroblasts during gastric carcinogenesis, and that aberrant expression of Cxcl12 accelerates gastric cancer development." (PMID 29340033, 2017). "In addition, CXCR7 is also a receptor for CXCL12 that binds this chemokine with greater affinity, the clinical and prognostic implications of CXCL12/CXCR4/CXCR7 axis in patients with gastric cancer remain to be elucidated in future." (PMID 23936528, 2013). "Cancerous CXCL12 positivity was determined to be an independent prognostic factor for patient survival of gastric cancer and CXCR4 expression was associated with lymph node and liver metastasis of gastric cancer." (PMID 23936528, 2013). "Furthermore, suppression of receptor expression led to downregulation of migration and invasion induced by the ligand CXCL12 in both breast and gastric cancer cells." (PMID 21880153, 2011). "Therefore, we investigated whether KDM6B plays a cancer promoting role in gastric cancer cells that depends on the CXCL12/CXCR4 signaling pathway." (PMID 36564369, 2022). "Overall, the novelty of our research lies in our integration of bioinformatics analysis, cell biology and clinical pathology evidence, and we proposed the mechanism of GC cell-CXCL12-CAFs-EMT in gastric cancer." (PMID 33854601, 2021). "Thus, we believe that Cxcr4+ epithelial cells, which include the Mist1+ antral progenitors, contribute to human gastric cancer progression, and that the Cxcr4/Cxcl12 axis may still be a promising therapeutic target against broad spectrum of gastric cancers." (PMID 29340033, 2017).